PTH (parathyroid hormone)
Diseases named in the same sentence as PTH in open-access papers (continued):
Sharing a sentence is not in itself a finding about the gene and the disease.
osteoporosis (continued). "Literature evidence describing a seeming de novo occurrence of severe osteoporosis accompanied by the presence of parathyroid adenoma with normal serum parathormone level (PTH), normal serum vitamin D, and serum calcium levels is rare; hence, this case report." (PMID 39697923, 2024). "Para thyroid hormone (PTH), an anabolic hormone, is given to patients with osteoporosis." (PMID 38891042, 2024). "Teriparatide, a recombinant form of human parathyroid hormone, acts as an osteoanabolic agent, increasing BMD and reducing the incidence of fragility fractures in postmenopausal women and cases of glucocorticoid-induced osteoporosis." (PMID 39624554, 2024). "Hyper- and normocalcemic patients were compared with regard to the proportion of osteoporosis and osteopenia, T-Score, TBS, serum calcium, phosphorus and parathyroid hormone levels, the maximum standardized uptake value (SUVmax) in PET/CT imaging, and laboratory results." (PMID 39594132, 2024). "Teriparatide, a recombinant human parathyroid hormone (PTH) composed of the hormone’s 1–34 amino acids, has been approved by the Food and Drug Administration (FDA) for the treatment of adults with severe osteoporosis." (PMID 38625587, 2024). "A higher value of 0.636 was seen adding osteoporosis (present or not) to the model (model 2), and an area under the curve of 0.687 adding osteosarcopenia (present or not), BMI and the parathyroid hormone level (model 3)." (PMID 39513358, 2024). "We did not adjust for anti‐osteoporosis medications (ie, bisphosphonates, parathyroid hormone analogs, and receptor activator of NF‐κB [RANK] ligand inhibitors) given the very low prevalence of these medications in our cohort (n = 14, less than 1%)." (PMID 37701146, 2023). "PTH and ALN are the most commonly used drugs for the prevention of osteoporosis." (PMID 37587136, 2023). "For the case of GIO, which is the largest cause of secondary osteoporosis, some studies have not found an association between GIO and increased PTH concentration." (PMID 36996072, 2023). "The main treatment for osteoporosis is pharmacological, including bisphosphonates (such as alendronate or ibandronate), hormone therapy (estrogens), calcitonin, denosumab (RANKL/RANK inhibitor), parathyroid hormone (PTH), and analogs." (PMID 37630580, 2023). "The formation and development of osteoporosis are regulated by various bone-related transcription factors and genetic factors at the molecular level, including transforming growth factor β (TGF-β), parathyroid hormone (PTH), and fibroblast growth factor (FGF)." (PMID 36979418, 2023). "Osteocytes express parathyroid hormone (PTH)/PTH-related protein (PTHrP) receptors and respond to the PTHrP analog abaloparatide (ABL) and to the PTH 1-34 fragment teriparatide (TPTD), which are used to treat osteoporosis." (PMID 37870958, 2023). "Based on these findings, the authors suggested that abnormalities in orderly pulsatile PTH secretion are unlikely to play a major role in driving PMO related osteoporosis." (PMID 36996072, 2023). "In addition, there is little information regarding PTH therapy for osseointegration after improved primary stability in low BMD sites, such as those present after glucocorticoid-induced osteoporosis." (PMID 35675357, 2022). "Taken together, our results suggested that a combination therapy of PTH and ZOL might be a promising approach for the intervention of early-stage implant loosening in patients with osteoporosis." (PMID 35546997, 2022). "Relevant studies were obtained using inclusion criteria: osteoporosis and serum, bone or bone cells and exclusion criteria: chondrocytes, secondary osteoporosis, no treatment with PTH or no direct effects of PTH on miRNA expression." (PMID 36011354, 2022).
osteoporosis (continued). "When suffering from osteoporosis, the secretion of PTH was reduced to inhibit the activity of osteoclasts, thus impeding the progression of osteoporosis, which might be the plausible explanation for the relationship between IBS and reduced level of PTH." (PMID 36501135, 2022). "In the present study, the combined treatment and monotherapy of PTH and ZOL enhanced periprosthetic bone volume and bone-implant contact and intramedullary implant stability in a debris wear-induced periprosthetic osteolysis under a condition of osteoporosis." (PMID 35546997, 2022). "INS, BGLAP, PTH, IGF1, and TNF were the top 5 most studied genes between osteoporosis and DM." (PMID 35719662, 2022). "For the osteoporosis-like phenotype GDD with low bone mass and low bone turnover, injectable PTH could be the best osteoanabolic treatment currently available for bone formation and activating WNT signaling in osteoblasts." (PMID 35982081, 2022). "Although it is considered safe to use in adults with osteoporosis and for replacement therapy in hypoparathyroidism, we suggest not to use recombinant PTH." (PMID 36149449, 2022). "Taken together, our results suggested that combination therapy of PTH and ZOL might be a promising approach for the intervention of early-stage implant loosening in patients with osteoporosis." (PMID 35546997, 2022). "When compared with the no-nutritional risk group, the nutritional risk group had a longer diabetes course, older age, lower BMI, lower ABL, higher HbA1c, lower TG, lower Ca, lower 25 (OH) D, lower PTH, lower femoral neck BMD, lower total hip BMD and higher prevalence of osteoporosis." (PMID 36494810, 2022). "With regard to laboratory data, mean serum phosphate levels and Kt/V ratios were higher in the osteoporosis group, whereas serum albumin, serum calcium, and serum intact PTH levels were not significantly different." (PMID 33462371, 2021). "In addition, PTH also promotes HBMSC proliferation, maintains HBMSC integrity, and slows down age-related osteoporosis in adult mice by reversing HBMSC apoptosis." (PMID 34350461, 2021). "Parathyroid hormone (PTH) and alendronate (ALN) are both used for the treatment of osteoporosis." (PMID 33436871, 2021). "Recombinant human PTH (Teriparatide; amino acids 1 to 34) and synthetic PTH-related protein (Abaloparatide) are approved by the US Food and Drug Administration (FDA) for the treatment of osteoporosis." (PMID 34140410, 2021). "The patient showed no signs of osteoporosis in the blood tests, with normal levels of serum 1,25-hydroxyvitamin D (vitamin D), parathyroid hormone (PTH), ß-CrossLaps and alkaline bone phosphatase." (PMID 34053464, 2021). "Parathyroid hormone (PTH) has been approved by the US Food and Drug Administration (FDA) since 2002, when teriparatide, a 34–amino acid analog of PTH, was accepted for the treatment of osteoporosis." (PMID 34101904, 2021). "Their daily activities, underlying diseases, biochemical indexes, 25(OH)D, sex hormones, parathyroid hormone levels (PTH), bone turnover markers, BMD, muscle strength, muscle function, balance function, and use of anti-osteoporosis drugs were analyzed and prospectively observed for 12 months." (PMID 33568077, 2021). "Since the surgery, calcium concentration and PTH levels have been within the normal range and the patient has no signs or symptoms of nephrolithiasis or osteoporosis." (PMID 33807230, 2021). "According to these evidences, as PTH levels have decreased significantly in the EG, the fortification of dairy products could provide a greater advantage against accelerated bone resorption in women at risk of osteoporosis, compared to equivalent non-fortified foods." (PMID 32722015, 2020). "The current drugs for the treatment of osteoporosis mainly include RANKL inhibitors and bisphosphonates, estrogen or selective estrogen receptor modulators (SERMs), calcitonin, strontium salts, and parathyroid hormone (PTH)." (PMID 33281915, 2020).
osteoporosis (continued). "In addition, individuals in the osteoporosis group had lower creatinine, and as a result, eGFR was higher and in umbilical cord blood, 25(OH)D was lower and β-CTX and PTH were higher compared with controls." (PMID 33315972, 2020). "Some variables, such as serum vitamin D and parathyroid hormone (PTH) levels, may change due to other pathological conditions in addition to osteoporosis." (PMID 32731479, 2020). "Excluding 39 patients with known osteoporosis and those who had taken bisphosphonates, denosumab or synthetic human parathyroid hormone within the 12 months before inclusion did not change our results for the BTM levels." (PMID 33046053, 2020). "A recent randomized controlled trial has reported full patient compliance and no adverse events from therapy with parathyroid hormone (PTH) for osteoporosis and accelerated healing of fragility fractures of the pelvis." (PMID 31332508, 2020). "Unfortunately, the duration of this therapy is limited to 2 years over a patient's lifetime and patients must continue using other osteoporosis therapies after PTH therapy is no longer available." (PMID 31781240, 2019). "Fifth, this study did not include newer osteoporosis drugs such as parathyroid hormone, selective estrogen receptor modulator, and anti-receptor activator of nuclear factor-kappaB antibody for analyses." (PMID 31307521, 2019). "In conclusion, serum PTH, osteocalcin, and alkaline phosphatase are associated with an adverse cardiovascular outcome 3 years after CABG surgery regardless of osteopoenia/osteoporosis, coronary/peripheral atherosclerosis, and CAC." (PMID 31597282, 2019). "Parathyroid Hormone (PTH) and its analogue Teriparatide (TPD) provide the possibility of improving skeletal microarchitecture and represent a new class of anabolic therapies for the treatment of severe osteoporosis." (PMID 30090207, 2018). "Neither vitamin D nor vitamin K levels were statistically different between patients with and without osteoporosis, while the mean value of PTH was significantly higher (70 ± 62 pg/ml vs. 43 ± 16 pg/ml; P = 0.002) in patients with osteoporosis." (PMID 30323223, 2018). "Regarding anti-osteoporosis medications, the overall results of the post hoc analysis (Tukey’s HSD test) clearly showed that PTH was the medication that exhibited the most pronounced bone-stimulating effect compared with ALN and control (saline), based on RT value, BIC, and BV/TV." (PMID 29531334, 2018). "Human PTH regulates calcium homeostasis as well as bone formation and resorption via activation of the PTH1R – as such it is a possible target in treating the highly prevalent age-related bone disorder osteoporosis." (PMID 30546309, 2018). "C-terminal cross-linked telopeptide of type I collagen (CTx), Osteocalcin (OC), parathyroid hormone (PTH), and N-terminal propeptide of type I collagen (P1NP), which can be utilized to monitor the progress of osteoporosis, were quantified using their corresponding antibody immobilized in membranes." (PMID 30181433, 2018). "In previous reports, intermittent ABL administration showed robust bone mineral density (BMD) increase and reduced the incidence of fractures in patients with osteoporosis, while its calcemic effect was reduced, as compared with teriparatide (TPTD), a parathyroid hormone N-terminal fragment." (PMID 29725706, 2018). "Therefore, this study is of high clinical value for defining the correlation between the levels of bone metabolic markers (such as VD and PTH) and BMD of perimenopausal women in Xi'an region, and guiding early clinical diagnosis and treatment of osteoporosis." (PMID 28686649, 2017). "Some of the limitations of this study were the absence of external quality control for vitamin D, PTH, and bone turnover markers and the absence of local data base to be used for identifying subjects with osteoporosis." (PMID 28124221, 2017).
osteoporosis (continued). "Third, this study investigated the trabecular structure only in the lower part of the mandibular first molar and did not explore the effect of intermittent PTH on treating osteoporosis of the maxilla or cortical bone." (PMID 28438150, 2017). "Although BPs plus PTH is not recommended for management of osteoporosis, immediate use of BPs after withdrawing teriparatide can increase BMD at lumbosacral." (PMID 28173850, 2017). "OPG, BMP and PTH have been reported as the most promising molecules for osteoporosis treatment, but not many new molecules have been studied as possible targets in this regard." (PMID 28173850, 2017). "The concern with PTH therapy in osteoporosis is that the use of PTH is limited to no more than 2 years and that treatment with anti-resorptive agents sequentially after withdrawal of PTH is required to maintain bone mass." (PMID 28246925, 2017). "PTH analogous are not recommended as first-line drug given to the cost of PTH analogous, subcutaneous (SC) route of administration, and the availability of other pharmacological agents for treating osteoporosis." (PMID 28173850, 2017). "While PTH has shown its potent anabolic effect in relation to osteoporosis, it has not been approved for use in cancer patients due to the potential increased risk for tumor development, specifically osteosarcoma." (PMID 27332712, 2016). "Hypoparathyroidism and osteoporosis can be treated with PTH injections; however, no orally effective PTH analogue is available." (PMID 27857062, 2016). "Parathyroid hormone (PTH) is a major research topic in increasing bone mass, and it is the only anabolic bone therapeutic option approved by the Food and Drug Administration (FDA) for patients with low bone mass conditions, such as osteoporosis, to date." (PMID 27997614, 2016). "In our case, however, despite the evident condition of hypovitaminosis D, the normality of all the other laboratory tests (especially PTH and beta-cross laps, important markers of bone remodeling) and the DEXA examination, make the diagnosis of osteoporosis at least unlikely." (PMID 24602357, 2014). "Drugs with limited anti-tumor activity but which are anabolic for bone include intermittent parathyroid hormone and antibodies that neutralize the WNT inhibitors DKK1 and sclerostin, as well as the activin A blocker sotatercept and the osteoporosis drug strontium ranelate." (PMID 25757219, 2014). "In a follow-up study this group provides evidence, using wild-type and OSMRβ deficient mice, that OSM participates in the anabolic effects of parathyroid hormone and thus may be integrated mechanistically into PTH standard therapy for osteoporosis in humans." (PMID 24381786, 2013). "Therefore, PTH or analogue and PTHR1 are potential novel targets for the therapeutic strategy for osteoporosis." (PMID 22312238, 2012). "Above-normal PTH levels were detected in 17.4% of postmenopausal women treated for osteoporosis, and a negative correlation was found between PTH and vitamin D levels." (PMID 23227959, 2012). "As more studies comparing the effects of PTH and bisphosphonates on BMD in patients with osteoporosis are now becoming available, we decided to perform a meta-analysis on the effects of PTH and bisphosphonates on BMD for the treatment of osteoporosis." (PMID 22022584, 2011). "Clinical evidence has shown that there can be a negative interaction between alendronate and intermittent parathyroid hormone, the only anabolic drug currently licensed for osteoporosis treatment." (PMID 21497678, 2011). "In order to determine other factors that might influence osteoporosis, we explored TFT's, testosterone, 25-OH vitamin D and PTH levels." (PMID 21138571, 2010). "In experimental and clinical osteoporosis, increased bone formation without increased bone resorption often occurs in the initial stages of response to PTH, whereas catabolism occurs within the context of increased remodeling after approximately 6 months." (PMID 21188144, 2010).
osteoporosis (continued). "BMS compound 1 has such a short acting profile in vivo in rats resulting in PTH bursts, but the effect of the compound on BMD has yet to be studied and the hypothesis of use of calcilytics for treatment of osteoporosis thus remains to be proven." (PMID 19305800, 2007). "After 24 months of treatment, PHPT patients experienced significantly increased BMD at femur, total hip, and spine compared to baseline values as well as compared to primary osteoporosis patients, whereas no change was observed in laboratory values including calcium, PTH, and ALP." (PMID 40177730, 2025). "Therefore, the sixteen variables, including Age, Diabetes, HB, TP, ALB, HDL-C, β-CTX, PTH, CSA, VB, FDR, 25-OH-D3, Number of fractured vertebrae, BMD, Exercise regularly after discharge, Anti-osteoporosis after discharge, were included in the multivariate Logistic regression model." (PMID 39911860, 2025). "Investigating the timing of melatonin administration inevitably brings to mind the potential mirror with the pulsatile PTH therapy used to stimulate bone formation in osteoporosis treatment, as opposed to the continuous PTH elevation seen in hyperparathyroidism." (PMID 40452254, 2025). "The management of osteoporosis typically focuses on bone-specific interventions, such as bisphosphonates, monoclonal antibodies targeting receptor activator of NFκB ligand (RANKL), selective oestrogen receptor modulators (SERMs), and parathyroid hormone (PTH) analogues." (PMID 41460797, 2025). "Disruption in this coupling in osteoporosis is mediated by a multifaceted interplay of biomolecules including, but not limited to cytokines (such as RANKL, OPG, and interleukins), growth factors (e.g., TGF-β and IGF-1), and hormones (including estrogen, testosterone, and parathyroid hormone)." (PMID 38841589, 2024). "Osteoporosis and other degenerative bone disease treatment strategies regularly employ bisphosphonates, hormone replacement therapy (HRT), selective oestrogen receptor modulators (SERMs), parathyroid hormone (PTH) analogues, or receptor activator of nuclear factor-kappa B ligand (RANKL) inhibitors." (PMID 39057021, 2024). "The present observational retrospective study with a long follow-up period is the largest case report study so far of treatment of osteoporosis with denosumab in patients with decreased kidney function and normal/high serum parathyroid hormone level, i.e., without adynamic bone." (PMID 37495795, 2023). "The physiologic balance between PTH action and established Wnt-pathway inhibitors, with their altered interplay in the presence of hyperparathyroidism, may explain the skeletal involvement in PHPT, which can range from normal bone to severe osteoporosis." (PMID 37841984, 2023). "Taken with the data that high dietary Pi intake stimulates PTH secretion independently of age, the chance of secondary hyperparathyroidism in the elderly would be compounded in the context of a habitual HPD and could exacerbate senile osteoporosis." (PMID 37079375, 2023). "PTH, via RANKL, may be responsible for diffuse osteoporosis in AS." (PMID 37841984, 2023). "In contemporary times, the non-specific skeletal effects of PTH excess such as cortical thinning, low bone mass and osteoporosis are more common than the specific bone lesions such as subperiosteal bone resorption, brown tumors, OFC, and pathological fractures." (PMID 36817587, 2023). "Thus, our findings indicated that combination or monotherapy with PTH and/or ZOL might be a promising strategy for preventing early-stage implant loosening in patients with severe osteoporosis." (PMID 35546997, 2022). "The current clinical treatment of osteoporosis is with drugs such as bisphosphonates, which are highly irritating to the gastrointestinal tract; parathyroid hormone requires daily subcutaneous injections and is expensive; calcium supplementation and vitamin D3 are not effective for osteoporosis." (PMID 36132487, 2022).